RNU6-571P (RNA, U6 small nuclear 571, pseudogene)
Gene: Small nuclear RNA gene on chromosome 10 (68,911,653 to 68,911,759, reverse strand). Ensembl gene ENSG00000206855.
Homologues: Orthologues: chimpanzee U6 (99% identical), macaque U6 (93% identical), rat LOC120102603 (71% identical), guinea pig U6 (66% identical). Paralogues in human: RNU6-43P (88% identical), RNU6-23P (87% identical), RNU6-831P (87% identical), RNU6-1042P (86% identical), RNU6-698P (86% identical), RNU6-727P (86% identical), RNU6-884P (86% identical), RNU6-944P (86% identical), RNU6-1091P (85% identical), RNU6-188P (85% identical), RNU6-214P (85% identical), RNU6-24P (85% identical), and 1286 more.